CD27 (CD27 molecule)
Description:
Costimulatory immune-checkpoint receptor expressed at the surface of T-cells, NK-cells and B-cells which binds to and is activated by its ligand CD70/CD27L expressed by B-cells. The CD70-CD27 signaling pathway mediates antigen-specific T-cell activation and expansion which in turn provides immune surveillance of B-cells. Mechanistically, CD70 ligation activates the TRAF2-PTPN6 axis that subsequently inhibits LCK phosphorylation to promote phenotypic and transcriptional adaptations of T-cell memory. In addition, activation by CD70 on early progenitor cells provides a negative feedback signal to leukocyte differentiation during immune activation and thus modulates hematopoiesis (By similarity). Negatively regulates the function of Th2 lymphocytes in the adipose tissue (By similarity).
Synonyms: TNFRSF7; S152; Tp55; S152. LPFS2; T14
Tractability: Antibody: a drug acting on it is in phase 2 or 3 trials; UniProt places it where antibodies can reach, with high confidence; its Gene Ontology location is reachable by antibodies, with high confidence; UniProt predicts a signal peptide or a membrane-spanning region. PROTAC: ubiquitination databases record sites on it.
Target class: Surface antigen
Gene: Protein-coding gene on chromosome 12 (6,444,941 to 6,451,718, forward strand). Ensembl gene ENSG00000139193.
Subcellular location: Cell membrane
Subcellular location (Human Protein Atlas): Vesicles
Pathways (Reactome):
Immune System: TNFs bind their physiological receptors
Gene Ontology:
Molecular function: cysteine-type endopeptidase inhibitor activity involved in apoptotic process; protein binding; transmembrane signaling receptor activity
Biological process: adaptive immune memory response involving T cells and B cells; CD27 signaling pathway; extrinsic apoptotic signaling pathway; negative regulation of apoptotic process; T cell activation; cell surface receptor signaling pathway; immunoglobulin mediated immune response; positive regulation of B cell differentiation; positive regulation of JNK cascade; positive regulation of non-canonical NF-kappaB signal transduction; positive regulation of T cell differentiation
Cellular component: plasma membrane; external side of plasma membrane; extracellular region; cell surface
Genetic constraint (gnomAD): Loss-of-function variants: 18 observed, 28.21 expected, observed/expected ratio (o/e) 0.64, 90% interval 0.44 to 0.95. The upper end of that interval is the gene's LOEUF score, 0.95, which puts it in group 4 of 6, group 1 being the genes least tolerant of losing a copy. Missense variants: 300 observed, 344.83 expected, observed/expected ratio (o/e) 0.87, 90% interval 0.79 to 0.96. Synonymous variants: 142 observed, 128.18 expected, observed/expected ratio (o/e) 1.11, 90% interval 0.97 to 1.27.
Homologues: Orthologues: chimpanzee CD27 (99% identical), dog CD27 (73% identical), rabbit CD27 (73% identical), pig CD27 (68% identical), rat Cd27 (67% identical), mouse Cd27 (64% identical), guinea pig CD27 (51% identical), zebrafish hdr (19% identical), zebrafish tnfrsf1b (17% identical), zebrafish tnfrsfa (17% identical), tropical clawed frog nradd (16% identical), zebrafish cd40 (16% identical), and 2 more. Paralogues in human: TNFRSF9 (25% identical), LTBR (20% identical), TNFRSF1B (20% identical), TNFRSF11A (19% identical), TNFRSF1A (19% identical), NGFR (18% identical), TNFRSF21 (18% identical), TNFRSF25 (17% identical), TNFRSF8 (17% identical), CD40 (16% identical), TNFRSF14 (16% identical), RELT (15% identical), and 9 more.
Diseases named in the same sentence as CD27 in open-access papers:
CD27 is named in the same sentence as 325 diseases in open-access papers, as found by Europe PMC text mining. Sharing a sentence is not in itself a finding about the gene and the disease. The quoted sentences say what the papers report.
COVID-19 (80 papers, 2020 to 2025). A disease caused by infection with severe acute respiratory syndrome coronavirus 2. "Moreover, altered frequencies of CD4+ and CD8+ T cell subsets including expansion of CD27- Tem, reduction of Tfh and Treg, increase of class-switched memory B cells, and loss of naive B cells were features of ASyS with severe or fatal COVID-19." (PMID 38500883, 2024). "RA and COVID-19 hospitalization, severe COVID-19 have two same immune cells phenotypes (CD27 on IgD + CD24 + B cell and CD3 on CD39 + CD8 + T cell), but it does not have the same immune cells as SARS CoV-2 infection." (PMID 40495223, 2025). "Considering the significant depletion of GC and reduced T cell/B cell interaction in the ileal follicles in PP of COVID-19 patients, we next evaluated the CD27 and CD74 expression by B cells." (PMID 35251032, 2022). "Consistent with the potential difference in GC activity and class switching observed above, we found that CD27+ IgD- switched memory (SM) B cells were significantly more frequent in HIV-ve COVID-19 patients than in PLWH." (PMID 36300787, 2022). "Lower circulating CD27+CD28+CD45RA+CCR7+ ‘naïve’ CD4+ T cell counts predicted a poor prognosis in patients with acute COVID-19." (PMID 35632823, 2022). "We also observed that the subpopulation of CD38++CD27 transitional B cells was decreased, while mature activated B cells (CD27+CD38+) and resting memory B cells (CD27+CD38−) frequencies increased in most subjects from both groups of COVID-19 patients." (PMID 35807783, 2022). "As for memory B cells, the level of CD27+IgD+IgM+ cells in patients with COVID-19 was significantly lower than the control values." (PMID 35632823, 2022). "The frequency of IgD+CD27+ and IgD–CD27+ B cells was significantly reduced in severe COVID-19 cases." (PMID 34696395, 2021). "Patients with severe and critically ill course of COVID-19 had lowered percentage of memory IgD+CD27+ B cells, whereas solely severe patients had profoundly decreased in memory IgD−CD27+ B cell subset compared to healthy volunteers." (PMID 35723393, 2021). "The proportion of EM (CCR7+, CD45RA−, CD28+ and CD27+/−) CD8+ T cells known to have higher concentration of GZMK is significantly decreased in the first week of COVID-19." (PMID 34945761, 2021). "The CD20dim/− PB populations of COVID-19 patients also encompassed more CD27+CD38+ cells as compared with recovered patients or healthy individuals (HD)." (PMID 34723157, 2021). "A recent study has reported a relative loss of peripheral blood CD45RA+CD27+CCR7+CD95− naïve CD4 T cells compared with the controls, but increased CD45RA−CD27−CCR7+ EM2 and CD45RA+CD27−CCR7− EMRA cells in patients with COVID-19 compared to the healthy donors." (PMID 34696395, 2021). "To isolate the monoclonal antibodies, we combined the PBMCs from 25 convalescent COVID-19 patients to enrich CD27+ memory B cells and activate memory B cells into plasmablast cells." (PMID 34539645, 2021). "Regarding this cytotoxic response, previous studies have shown that COVID-19 patients have decreased levels of CD8+ effector memory T cells (CD27-, CD45RA-), which is corroborated by our findings." (PMID 34566957, 2021). "Moreover, virus-specific T lymphocytes obtained from patients with severe COVID-19 tended to have a greater frequency of the central memory phenotype (CD27+/CD45RO+)." (PMID 40141410, 2025). "Moreover, we measured CD19+ and CD27(−) lymphocytes, and antibody-secreting cells, as these are closely related to antibody production and harbor a prognostic role in COVID-19 patients." (PMID 37897014, 2023). "However, severe COVID-19 patients had greater frequencies of CD27+ CD62L+ cells (p=0.02) within the total CD4+ T cell population." (PMID 36817450, 2023). "As these cells may home to lymph nodes or infected tissue, and severe COVID-19 is thought to be driven in part by an increase in activated T cells, we examined the expression of the activation markers CD27 and CD25 on the CD62L+ T cells." (PMID 36817450, 2023).
COVID-19 (continued). "Currently, we have shown that vitamin D supplementation could effectively decrease the relative numbers of activated CD38++CD27 transitional B cells and ‘naïve’ B cells in patients with acute COVID-19." (PMID 35807783, 2022). "The analysis of T-helper differentiation in peripheral blood revealed a relative loss of ‘naïve’ CD4 T cells (with CD45RA+CD27+CCR7+CD95− phenotype) but a significant increase in the amount of EM2 (CD45RA−CD27−CCR7+) and EMRA (CD45RA+CD27−CCR7−) cells in COVID-19 patients compared to controls." (PMID 35632823, 2022). "However, COVID-19 patients with a poor disease outcome demonstrated higher CD19+CD5+CD27+ cell levels compared to patients with a favorable disease outcome." (PMID 35337053, 2022). "At the same time, recent studies have found that S-specific memory B-cells with the IgD–CD21+CD27+CD38–CD71int/- phenotype are detected in patients who recovered from severe COVID-19 six months ago, suggesting that effective immunity can be induced even in this group of patients." (PMID 35632823, 2022). "Indeed, we found a transient increase of CD19+CD45RA+CD27+CD38bright plasmablasts in consecutive samples from COVID-19 patients." (PMID 35215797, 2022). "B cells expressing CD27 were depleted in GALT of COVID-19 patients evaluated here." (PMID 35251032, 2022). "Furthermore, COVID-19 survivors demonstrated decreased circulating CD19+CD27− B cells compared to patients with a poor outcome in the acute stage of the disease, while the CD19+CD27+ B cell numbers in this group were lower compared to controls or patients with a poor outcome." (PMID 35337053, 2022). "In COVID-19, circulating CD27+CD38+CD138+ B cells not only contained high levels of Ki67 in the cytoplasm but also expressed the activation marker CD95 on their membrane, which could indicate a recent migration of B cells from the germinal centers of lymphoid tissue." (PMID 35632823, 2022). "These CD11b+CD27+ NK cells which express c-Kit, are myeloid progenitor of neutrophils and monocytes, and may contribute to the persistent signs of immunomodulatory in convalescent severe COVID-19." (PMID 34867943, 2021). "In addition, we performed an analysis of B cells and, while the frequencies of CD27- B cells, which include mostly the naïve subset, tended to increase in COVID-19 patients, the frequencies of CD27+ memory B cells tended to decrease with the disease severity, although not significantly." (PMID 33777054, 2021). "Regarding circulating effector B cells, it was found that COVID-19 patients had upregulated level of Ki67 marker as well as surface activation marker CD95 in circulating CD27+CD38+CD138+ B cells that might suggest about recent emigration from germinal center of the secondary lymphoid tissues." (PMID 35723393, 2021). "Therefore, measuring CD19+IgD+CD27- naïve B cells may allow prediction of a humoral response to COVID-19 vaccination in immunocompromised patients." (PMID 34950155, 2021). "CD27, TNFRSF14, TNFRS18, and TNFRSF4 were highly expressed in the HLA_DR+ Tregs from severe COVID-19 patients." (PMID 40114921, 2025). "Analysis of CD8+ T-cells showed that, despite the disease outcome, an increased frequency of CD69+ and CD107a+, along with a decreased percentage of CD28+, CD27+, and CD45RO+ CD8+ T-cell subsets, were observed in both COVID-19 subgroups." (PMID 39597661, 2024). "Despite no changes in the frequency of CD8+ T-cells, increased frequencies of CD69+, CD107a+, T-bet+, and CD62L− and decreased percentages of CD28+, CD27+, and CD45RO+ CD8+ T-cells were observed for COVID-19 patients in comparison to HCs." (PMID 39597661, 2024). "Overall, our findings summarized a set of phenotypes feasible to be considered as potential predictors of COVID-19 outcome, including CD4+CD107a+, CD4+T-bet+, CD8+CD69+, CD8+T-bet+ and CD4+CD45RO+CD27+." (PMID 39597661, 2024).
COVID-19 (continued). "Several investigations have found that the number of switched (e.g., CD27 on IgD- CD38br) and unswitched (e.g., CD19 on IgD+ CD38-) memory B cells is significantly reduced in COVID-19 patients." (PMID 39224704, 2024). "The data also indicated a higher percentage of mature naive B cells (MN) (CD27−, CD38+), antibody-secreting plasmablasts (CD27+, CD38+), and resting memory B cells (RM) (CD27+, CD38−) in COVID-19 patients compared with healthy individuals." (PMID 39407725, 2024). "The results demonstrated that, at D0, nine cell subsets presented robust global accuracy (AUC ≥ 0.8) to classify COVID-19 vs. HCs, with outstanding performance (AUC = 0.9) observed for CD8+CD69+, CD4+CD38+, CD3+CD38+ and CD8+CD27+." (PMID 39597661, 2024). "Later at D14–28, 16 cell subsets presented elevated global accuracy (AUC ≥ 0.8) to classify COVID-19 vs. HCs, with AUC = 1.0 registered for CD4+CD38+ and CD8+CD69+ and AUC = 0.9 observed for CD8+CD27+, CD3+CD107a+, CD4+T-bet+, CD8+CD107a+ and CD3+CD38+." (PMID 39597661, 2024). "Within anti-TNF-α-treated patients, COVID-19 asymptomatic subjects had a trend to higher CD8+ total memory GZMB/K+, memory, and class-switched B cells, while TH1 and CD8+ CD27+ GZMB/K+ cells were comparable in symptomatic and asymptomatic subjects." (PMID 35757699, 2022). "In the case of memory B-lymphocytes (CD19+CD27+CD21+), a similar proportion of this population was detected between the COVID-19(−) and recovered COVID-19(+) participants." (PMID 36298626, 2022). "Our study found a high correlation between 8 target genes and immune cell markers (CD8, CD19, CD20, CD27, CD56, and CD66b), which further demonstrated the crucial role of 8 target genes in COVID-19 treatment." (PMID 35957855, 2022). "We isolated PBMCs from 16 COVID-19 convalescents using MERS-CoV S2 probes and sorted single memory B cells (CD19+/CD3-/CD27+/IgD-/IgG+)." (PMID 36618428, 2022). "COVID-19 asymptomatic b/ts-DMARD-treated patients had lower frequencies of TH1, CD8+ CD27+ GZMB/K+, and memory B IgG+ cells." (PMID 35757699, 2022). "The relative numbers of T and B cells, CD4+ T cells, CD8+ T cells, CD4+FoxP3+ T cells and the mean signals for PD-1, CD27 and CD45RO in T cells were similar between COVID-19 patient and control samples." (PMID 35251032, 2022). "The presence of CD27+CD20+ B cells and CD74hiCD20+ B cells were significantly reduced in PP from patients with COVID-19 compared to controls." (PMID 35251032, 2022). "Furthermore, staining the PBMCs of the COVID-19 convalescents with MHC-I multimers revealed that SARS-CoV-2-specific CD8+ T cells had effector memory (CD45RA−CCR7−) or central memory (CD45RA−CCR7+) phenotypes with early (CD27+CD28+) or intermediate (CD27+CD28−) differentiation." (PMID 34452355, 2021). "Compared to both healthy donor cohorts, we observed that more SARS-CoV-2-reactive T cells from COVID-19 patients expressed the activation markers CD38, CD39, CD69 and HLA-DR, and showed a late-differentiated effector memory profile of reduced CD27." (PMID 33853928, 2021). "Memory cells (CD27+CD45RA-) that express PD-1 and CD38 (Pop0) and PD-1, CD38 and HLA-DR (Pop2), as well as CD27-CD45RAlow expressing PD-1, CD38 and HLA-DR (Pop6) were also expanded in COVID-19 patients." (PMID 33777054, 2021). "In COVID-19 patients, the CD244 and PD-1 expression levels of CD8+ and CD4+ T cells were significantly higher and CD27 expression levels of CD8+ T cells were significantly lower than healthy controls." (PMID 33154753, 2020). "EMD group 2, containing mostly HDs and RDs, was enriched for naïve B cells (IgD+CD27−, cluster 10) and CXCR5+IgD−CD27+ switched memory cells (cluster 2), and indeed, clusters 2 and 10 were statistically reduced in COVID-19 patients." (PMID 32669297, 2020).
COVID-19 (continued). "At T0, COVID-19 led to a significant increase of CD27-IgD- DNM cells and decrease of CD27+IgD+ USM B-cell frequency in patients with moderate and severe disease, while classical memory B-cell percentage tended to decrease only in patients affected by severe disease." (PMID 39136010, 2024). "Therefore, in this study, we investigated and assessed the expression of CD27 and CD38 proteins on B cells to identify any changes in the circulating B cell subset in patients with severe COVID-19." (PMID 39407725, 2024). "Notably, lower frequencies of total and CD27+ CD8+ T-cells, together with increased frequency of CD69+, CD107a+, T-bet+, and PD-1+ CD8+ T-cell subsets, were observed in COVID-19 patients progressing to death as compared to those evolving to discharge." (PMID 39597661, 2024). "The CD27+CD28+ subset of T cells, commonly referred to as naïve T cells, play a critical role in mounting an effective immune response against novel viral infections such as COVID-19 or in response to vaccination." (PMID 37465793, 2023). "Although we had previously examined the antibody genes of IgG+S-RBD+ Bmems, we evaluated the CD19+CD27+IgG+ cell antibody gene because the S-RBD+ cell population was absent in the immunocompromised patient with prolonged COVID-19." (PMID 36366324, 2022). "Moderate and severe COVID-19 resulted in a significant decrease in CD27+ B cells, which account for memory B cells, in non-HD patients, which was not the case for HD patients with COVID-19." (PMID 35265078, 2022). "Although memory B cell (MBC) subsets such as class-switched (IgD-CD27+) and not class-switched (IgD+CD27+) appear to be decreased in severe COVID-19 compared to mild individuals, other authors have reported an increase in activated and resting MBCs." (PMID 36451829, 2022). "Thus, in patients with mild and severe COVID-19, the number of CD21+CD27+ cells in circulation reduced relative to the control, while the proportion of CD21–CD27– cells significantly increased." (PMID 35632823, 2022). "Compared to individuals tested negative for SARS-CoV-2, COVID-19 patients show a specific B cell population expressing cell surface marker CD27+CD38+." (PMID 36369012, 2022). "Moreover, for COVID-19 convalescents, lower expression levels of CXCR5 on IgD+CD27+ and IgD–CD27+ memory B cells were also noted, which indicates a durable impairment in B cell function during the period of recovery." (PMID 35632823, 2022). "Furthermore, more individuals recovered from severe and critical COVID-19 showed reduced frequencies of central memory (CM) CD4+ and CD8+ T cells (defined as CD45RA−CCR7+CD27+) (Bonferroni-adjusted P-value range 0.02–7.61 × 10−6)." (PMID 36433939, 2022). "Moreover, COVID-19 patients with poor disease outcomes had higher percentages of CD19+CD27− and CD19+CD27+ B cells in circulation than patients with favorable outcomes." (PMID 35337053, 2022). "CD27 and increased expression of CXCL13 may support blast response from B cells, as is seen in COVID-19, further propelling vascular inflammation and lung injury." (PMID 34177897, 2021). "Of note, the frequency of CD21+CD27+ non-plasmablasts was directly correlated with donor age among moderate and severe COVID-19." (PMID 32669287, 2020). "Focusing on B cells, patients with severe COVID-19 displayed a dramatic expansion of CD27–IgD– double negative (DN) B cells." (PMID 32943497, 2020). "The only subpopulation of B cells dramatically expanded in patients with severe COVID-19, compared to patients with mild and moderate disease, was double negative (DN) B cells (CD27–IgD–)." (PMID 32943497, 2020). "Whereas naïve B cell frequencies were similar in COVID-19 patients and RDs or HDs, the frequencies of class-switched (IgD−CD27+) and not–class-switched (IgD+CD27+) memory B cells were significantly reduced." (PMID 32669297, 2020). "However, the frequency of both class-switched (IgD−CD27+) and not–class-switched (IgD+CD27+) B cells were lowered in COVID-19 patients." (PMID 36369012, 2022).